IL6 (interleukin 6)
Diseases named in the same sentence as IL6 in open-access papers (continued):
Sharing a sentence is not in itself a finding about the gene and the disease.
Chagas disease (29 papers, 2013 to 2025). A parasitic infection caused by Trypanosoma cruzi. "Indeed, IL-6 has a critical role in regulating inflammasome activation and IL-1β-induced NO production early after pathogen encounter in a murine model of T. cruzi infection (the causal agent of Chagas disease)." (PMID 37818368, 2023). "The combined mitogenic effects, the production of inflammatory mediators, such as IL8 and IL6, and the ability to facilitate infection underscore the important role of cTXNPx in the pathogenesis of Chagas disease." (PMID 38251374, 2024). "It is therefore suggested that IL-6 is an important marker of cardiac tissue damage and systemic vascular inflammation in Chagas disease with prognostic value." (PMID 39598539, 2024). "Here, we demonstrated that STING signaling is required for production of IFN-β, IL-6, and IL-12 in response to Trypanosoma cruzi infection and that STING absence negatively impacts activation of IRF-dependent pathways in response to the parasite." (PMID 35095849, 2021). "In the present work, we first determined the spontaneous expression of pro-inflammatory mediators, such as MCP-1 and its receptor CCR2, and IL-12, TGF-β, IL-6 in cultured PBMC from seropositive patients with different clinical forms of Chagas disease." (PMID 35360222, 2021). "IL-6 improves the cytotoxic CD8+ T cell dysfunction triggered by nitric oxide in patients with Chagas disease; additionally, we recently demonstrated that IL-17RA and IL-17A are critical factors for sustaining CD8+ T cell immunity to T. cruzi." (PMID 32398312, 2020). "Elevated IL-6 levels, myositis, periganglionitis, and ganglionitis, as a result of high parasite load of Trypanosoma (T.)cruzi, the protozoan responsible for Chagas Disease, were described." (PMID 30744559, 2019). "The expressions of different cytokines (IL-10, IFN-γ, TNF-α, IL-6, IL-1β) were evaluated in the plasma of healthy individuals and patients with different forms of Chagas disease." (PMID 24603474, 2014). "A novel contribution of this study is the possibility of using IL-12, IFN-γ, IL-6 and IL-1 as prognostic biomarkers of Chagas Disease." (PMID 24608170, 2014). "Moreover, the treatment of mice with rlL9 was linked with decreased levels of IL-12, IL-6, and TNF-α levels in Chagas disease." (PMID 36293524, 2022). "It is possible, therefore, that other factors may also play a role in determining IL6 levels that modulate the cardiac phenotype in Chagas disease." (PMID 33193300, 2020). "Furthermore, chronic patients with Chagas disease have elevated circulating levels of IL-6 when compared to healthy individuals." (PMID 31139194, 2019). "In fact, it has been described that IL-6 induces epidermal cell proliferation and thickening of stratum corneum, increasing skin protection from infection, which is probably occurs during skin manifestations of Chagas disease." (PMID 30038622, 2018). "We found again in both groups, I and II, that IL-12, IFN-γ, IL-6 and IL-1 are the principal components and thus they may play an important role in Chagas disease pathophysiology." (PMID 24608170, 2014). "It appears that IL6 gene polymorphism does not contribute to susceptibility in the clinical manifestations of Chagas disease." (PMID 24069594, 2013). "Finally, we examined peripheral and myocardial parasite burden, plasma levels of myeloperoxidase and IL-6, and myocardial inflammatory infiltrate and LDH expression to evaluate the effect of parasite and MnSOD deficiency on inflammatory stress in Chagas disease." (PMID 30044789, 2018). "During Trypanosoma cruzi infection, the immune system activates a robust inflammatory response, involving cytokines and chemokines like IFN-γ, TNF, IL-6, IL-1β, CCL2, and CCL5, to control parasite replication." (PMID 40936920, 2025).
Chagas disease (continued). "The results show that PBMC from Chagas disease patients display higher levels of IL-12, TGF-β, IL-6, MCP1, and CCR2 than cells from uninfected individuals (HI), irrespectively of the clinical stage, asymptomatic (Asy) or with Chagas heart disease (CHD)." (PMID 35360222, 2021). "Interestingly, chronic phase also demonstrated elevated IL-6 serum levels in response to infection and also in heart lysates when neutralizing IL-9, probably these cytokines can interplay a fine tune between beneficial inflammation and tissue damage throughout Chagas’ disease." (PMID 34722343, 2021). "We observed similar expression of TRIF, IL-6, IL-23 and IFN-α in chagasic patients with different clinical manifestations of Chagas disease." (PMID 30044791, 2018). "We observed an inverse and statistically significant correlation between the inflammatory cytokines TNF-α, IL-6 and IFN-γ with LVEF, a worse prognosis predictor in Chagas disease, while IL-17 plasma level was positively correlated with LVEF and LVDD, indicating better heart function." (PMID 38390336, 2024). "In our cohort of chronically infected Chagas disease patients, those with detectable T. cruzi parasitemia measured through RT-PCR in peripheral blood had a higher concentration of pro-inflammatory cytokines (TNF-α, IL-1β, IL-6 and IL-17A) and IL-4 than those with negative RT-PCR." (PMID 38133693, 2023).
Huntington disease (29 papers, 2009 to 2026). Huntington disease (HD) is a rare neurodegenerative disorder of the central nervous system characterized by unwanted choreatic movements, behavioral and psychiatric disturbances and dementia. "On the contrary, the knockout of IL-6 in a mice transgenic model of Huntington’s disease (HD) was reported to worsen the phenotype associated to HD leading to dysregulation of genes essential for synaptic functions and relevant for the pathogenesis of HD." (PMID 36675095, 2023). "Our own previous studies found a significant correlation between plasma and saliva for IL-6 (r = 0.590; p < 0.0001) in adult patients with Huntington’s disease and normal control subjects (aged 23–78 years)." (PMID 36319939, 2023). "In Huntington’s disease (HD), both human plasma and cerebrospinal fluid (CSF) had increased proinflammatory mediators, such as cytokines interleukin-6 (IL-6) and interleukin-8 (IL-8)." (PMID 33276471, 2020). "Furthermore, the calcium channel blockers verapamil and diltiazem significantly downregulate quinolinic acid-induced TNF-α and IL-6 levels in a rat model of Huntington’s disease." (PMID 37435081, 2023). "IL-6-mediated JAK2/STAT3 signaling cascade has been shown to contribute to neurodegeneration in AD and Huntington’s disease models." (PMID 33494411, 2021). "In an in vivo model, using 3‐nitropropionic acid (3‐NP) to induce Huntington's disease, CBG (10 mg·kg−1 per day i.p.)significantly attenuated the up‐regulation of COX‐2, iNOS, IL‐6, and TNF‐α." (PMID 32608035, 2020). "Essentially, abrogation of TNF-α and IL-6 alongside COX-2 downregulation mediated the neuroprotective effects of meloxicam in experimental LPS-evoked brain neuroinflammation, quinolinic acid-induced Huntington’s disease-like manifestations, and in a painful nerve root injury model." (PMID 37375795, 2023).
myositis (29 papers, 2012 to 2025). "Yet lately the recognition of Th17-associated cytokines such as IL-17, IL-22, and IL-6 in the blood and other areas of inflammation in some patients with myositis has challenged our current knowledge on the etiopathology of myositis." (PMID 31429786, 2019). "These cytokines were selected as readouts because IL-6 is known to associate with disease pathology in myositis and IL-10 is a marker of Bregs." (PMID 29988398, 2018). "Interleukin-6 (IL-6) is a pro-inflammatory cytokine implicated in the pathogenesis of myositis." (PMID 41373880, 2025). "However, in the last decade overexpression and elevated level of Th17-associated cytokines (IL-17, IL-22, and IL-6) were identified in the blood and the inflamed muscles of myositis patients." (PMID 31429786, 2019). "Interestingly, this conclusion was verified in an experimental mouse model of myosin-induced myositis, indicating that the deficiency of IL-6 led to marked amelioration of the clinical signs and pathologic findings of muscle injury." (PMID 24082909, 2013). "Furthermore, we have used transcriptomic analyses to identify a distinct type of ICI-associated myositis in patients with thymoma, which is characterized by a dense inflammatory infiltrate in muscle biopsies and activation of the interleukin (IL)-6 and type 2 interferon (IFN) pathways." (PMID 38611047, 2024). "According to our results, the elevated cytokines found in the myositis seronegative patients (IL-6, IL-23, IL-12p70, IL-33, and CXCL8) are related to a Th17 profile." (PMID 39456842, 2024). "They found increased IL-6 mRNA levels in the mice muscles (particularly in macrophages) which correlated with the histological severity of myositis." (PMID 37404372, 2023). "IL-6 was proved to be essential for the development of myositis, in this model, and its blockage suppressed the incidence and severity of myositis." (PMID 37404372, 2023). "Accordingly, in 2009, Okayama and colleagues published an elegant study refereeing to the critical role of IL-6 in a murine model of myositis." (PMID 37404372, 2023). "Interleukin-6 (IL-6), a pro-inflammatory cytokine, is expressed in the muscle biopsies of patients with different subtypes of myositis, including dermatomyositis." (PMID 35457124, 2022). "There is evidence for a potential role of IL-6 in the pathogenesis of myositis, and experimental mouse models suggest that IL-6 blockade alleviates the inflammatory response in muscle." (PMID 35394612, 2022). "An in vitro study on primary human muscle cell cultures from myositis patients showed that immunoproteasome is involved in the maintenance of myokines (IL-6, IL-1β, CXCL9, and CXCL10) production and in MHC I overexpression." (PMID 32775472, 2020). "Nivolumab monotherapy was started and myositis with an increase of myoglobulin was observed at day 98 with a parallel increase of IL6 as well as of S100B." (PMID 32188047, 2020). "In animal EAM models, it has been reported that IL-6 or IL-1 blockade diminishes the severity of myositis." (PMID 25161767, 2014). "This is pertinent to myositis as IL-6 is known to correlate with disease activity in idiopathic inflammatory myositis (IIM) and IL-6 blockade attenuates muscle inflammation in some mouse models." (PMID 24286299, 2013). "In ICI-myositis, there is evidence of upregulation of the IL-6 pathway, and hence, treatments such as tocilizumab may be favoured." (PMID 40647363, 2025). "Moreover, an anti-inflammatory effect was demonstrated in myositis murine model, shown by reduced interleukin 6 (IL-6) and tumor necrosis factor α (TNF-α) mRNA expression." (PMID 40943287, 2025). "Therefore, we suggest a possible differential immune response in seronegative myositis mediated by an induction of the Th17 inflammatory response, through IL-6, with maintenance of the Th17 pathway by IL-23 and IL-33." (PMID 39456842, 2024).
myositis (continued). "In conclusion, the role of IL-6 in myositis is not yet fully understood, and further studies on this cytokine as a therapeutic target should be considered, taking into account both the role of IL-6 as myokine, but also as a serum cytokine, or its dual role played in metabolism." (PMID 32775472, 2020). "We found higher serum levels of IL-10, IL-6, CXCL8, IL-1β, IL-33, IFN-γ, TNF-α, IL-23, and IL-17A in myositis patients compared to the HSs." (PMID 39456842, 2024). "Increased colon width, inflammatory infiltration, myositis, periganglionitis, ganglionitis, pro-inflammatory cytokines (e.g., TNF-α, INF-γ, IL-2, IL-17, IL-6), and intestinal amastigote nests were more pronounced in high parasite load-bearing animals." (PMID 25889515, 2015). "IL-1, IL-6, MCP-1, as well as TNFα, are increased in myositis muscle tissues and contribute to disease pathogenesis." (PMID 22577940, 2012). "The serum levels of anti-EJ, IP-10, IL-6, MCP-1, and VEGF may be related to disease activity in myositis patients with anti-EJ antibodies." (PMID 31019965, 2019). "The results of the present study do not report any myositis foci, which may be related to chronic infection in all cases, and therefore correlation to IL-6 expression is needed." (PMID 33409539, 2021).
post-traumatic stress disorder (29 papers, 2012 to 2025). An anxiety disorder precipitated by an experience of intense fear or horror while exposed to a traumatic (especially life-threatening) event. "Military personnel and veterans who sustained ≥ 3 TBI had higher serum IL-6 concentrations compared to controls, and these elevated IL-6 levels were associated with symptoms of posttraumatic stress disorder (PTSD)." (PMID 38336728, 2024). "Furthermore, posttraumatic stress disorder was found to cause upregulation of serum interleukin 6 (IL-6) and proinflammatory cytokines, such as interferon-gamma (IFN-γ), interleukin 1 β (IL-1β), interleukin 10 (IL 10), and tumor necrosis factor α (TNF α)." (PMID 34966477, 2021). "In addition, the post-traumatic stress disorder (PTSD) is associated with increased levels of IL-6, interleukin-1 beta (IL-1β), interferon gamma (INFγ) and tumor necrosis factor alpha (TNFα)." (PMID 32858844, 2020). "However, the dosage of other more specific factors, such as IL-6 or IL-10, may help to refine the diagnosis of patients at risk of post-traumatic stress disorder." (PMID 31805967, 2019). "The pathophysiology of posttraumatic stress disorder (PTSD) is associated with the activation of the innate immune system, including cytokines like interleukin 6 (IL-6)." (PMID 38613673, 2024). "Recently, DEFA4 was observed to be up-regulated in Japanese women with post-traumatic stress disorder (PTSD) who have elevated levels of IL-6 compared with those who have normal levels of IL-6, suggesting that DEFA4 up-regulation appeared to be correlated with high levels of IL-6." (PMID 35668817, 2022). "However, a chronic trauma/stress related disorder like post-traumatic stress disorder is associated with dysregulation of the HPA with resultant elevations of plasma NE, cerebral spinal fluid IL-6 levels, and cerebral spinal fluid substance P levels." (PMID 35295453, 2021). "In the context of this manuscript, the known correlation between chronic pain and post-traumatic stress disorder may be of significance as elevated levels of IL-6 (inflammation) and NE (vasoconstriction) would create the ideal interstitial environment for the development of IIS." (PMID 35295453, 2021). "Methylation of the AIM2 gene at the site cg10636246 drives the relationship between trauma exposure, posttraumatic stress disorder (PTSD), the level of C-reactive protein (CRP) and other inflammatory mediators, such as IL-6, IL-10, and TNF-α, in the body." (PMID 36742336, 2023). "Studies in mild and/or recurrent TBI should also consider more subtle functional outcomes such as return to work, post-traumatic stress disorder (PTSD) and neurocognitive sequelae such as fatigue, and their relationship to IL-6 levels." (PMID 35790656, 2022). "Furthermore, post-traumatic stress disorder (PTSD) is also characterized by inflammation dysregulation, determining changes in the levels of IL-6 and TNF-α." (PMID 39458125, 2024). "Several studies noted that veterans with post-traumatic stress disorder (PTSD) had elevated levels of IL-6 in cerebrospinal fluid (CSF) but not in plasma compared to controls." (PMID 36120298, 2022). "The outcomes were psychological well-being [perceived stress, depressive symptoms, loneliness, and post-traumatic stress disorder (PTSD)] symptoms and stress-related markers, including diurnal salivary cortisol and cytokines interleukin-6 (IL-6) and interferon gamma (IFN-γ)." (PMID 36042095, 2022).
silicosis (29 papers, 1996 to 2025). Silicosis is a respiratory disease caused by breathing in (inhaling) silica dust. "TNF a classical pro-inflammatory cytokine, stimulates fibroblasts proliferation and interacts with other inflammatory mediators, such as IL-1β, IL-6, and IL-8, to modulate immune responses and inflammatory reactions which are associated with silicosis." (PMID 40470053, 2025). "Conversely, the IL-6 -634 genotype was significantly associated with the lower risk of silicosis and CWP." (PMID 40182855, 2025). "IL-8, LDH, andAAT levels were associated with progression of silicosis, and IL-6, IL-8, LDH, AAT,ferritin, and CRP levels were associated with a fatal outcome." (PMID 39606764, 2024). "IL-8, LDH and AAT levels were associated with progression of silicosis and IL-6, IL-8, LDH, AAT, ferritin, and CRP with vital status." (PMID 34172787, 2021). "The IL-6 -634 mutant significantly decreased silicosis and CWP risk." (PMID 40182855, 2025). "Moreover, the IL-6 -634 G-allele mutant decreased the predisposition to silicosis and CWP risk, respectively." (PMID 40182855, 2025). "Therefore, we performed this meta-analysis to precisely evaluate the association between the IL-1α +4845G/T, IL-1β +3953C/T, IL-1RA +2018T/C, IL-1β -511C/T, IL-6 -634C/G, IL-6 -174G/C, and IL-17A -832A/G polymorphisms and silicosis susceptibility." (PMID 40182855, 2025). "Similarly, with a prior probability of 0.25, the allelic, homozygous, heterozygous, and dominant models of the IL-6 -634 polymorphism were correlated with silicosis (p < 0.2)." (PMID 40182855, 2025). "Also, SiO2 induced macrophage senescence and silicosis in lung tissue, both of which were accompanied by increased fibrosis-associated factors (IL-1β, IL-6, TNF, and TGF-β1) and MMPs (MMP2, MMP9 and MMP12)." (PMID 35959439, 2022). "Coincident with earlier findings, BIC suppressed TGF-β1 expression in BALF, serum, and lung tissues in our silicosis rat model, while the three other cytokines examined (IL-1β, IL-6, and TNF-α) were only decreased in BALF and lung tissue and not in serum." (PMID 39060930, 2024). "IL-6 differed between the complicated silicosis and simplesilicosis groups, with higher serum levels in patients with or without silicosisthan in unexposed healthy individuals." (PMID 39606764, 2024). "In the early stages of silicosis, M1 macrophages are stimulated, which promotes inflammation primarily through the production of the pro-inflammatory cytokines IL-1β and IL-6." (PMID 38515835, 2024). "Patients with silicosis seem to have a chronic inflammatory process that is consistent with the augmented levels of some pro-inflammatory cytokines, i.e., IL-1β, IL-6, IL-7, IL-8, IL-16, IL-17A, IL-33 and TNF-α were observed in this work." (PMID 36675056, 2023). "The expression of the inflammation-related factors interleukin 6 (IL 6) and interleukin 1β (IL 1β) were significantly up-regulated in the silicosis model group, but were consistent with the collagen deposition." (PMID 36430681, 2022). "In agreement with Szapiel scores, we found that both mRNA levels and protein concentration of IL-1β and IL-6 were all increased in silicosis mice, but were decreased in that of the Tet-treated silicosis mice." (PMID 34417574, 2022). "Compared with CG group, the secretions of serum TGF-β1, CTGF, TNF-α and IL-6 were significantly increased in the silicosis group." (PMID 35379204, 2022). "Previous findings suggest that patients with silicosis exhibited higher IL-6 serum levels than in unexposed healthy individuals, which is similar to our observations." (PMID 36311760, 2022). "In a recent clinical study, a group of silicosis patients was divided into two categories to evaluate a potential treatment for silicosis (acetylcysteine + tetrandrine) and its effect on serum IL-6 and TNF-α levels." (PMID 36672608, 2022).